OR14I1 (olfactory receptor family 14 subfamily I member 1)
Description:
Odorant receptor.
Synonyms: OR5BU1; OR5BU1P
Tractability: Antibody: UniProt places it where antibodies can reach, with medium confidence; UniProt predicts a signal peptide or a membrane-spanning region; its Gene Ontology location is reachable by antibodies, with medium confidence.
Gene: Protein-coding gene on chromosome 1 (248,678,138 to 248,702,766, reverse strand). Ensembl gene ENSG00000189181.
Subcellular location: Cell membrane
Pathways (Reactome):
Sensory Perception: Expression and translocation of olfactory receptors
Gene Ontology:
Molecular function: protein binding; odorant binding; olfactory receptor activity; G protein-coupled receptor activity
Biological process: sensory perception of smell; detection of chemical stimulus involved in sensory perception of smell; G protein-coupled receptor signaling pathway
Cellular component: plasma membrane; membrane
Homologues: Orthologues: chimpanzee OR14I1 (97% identical), macaque OR14I1 (93% identical), rabbit OR14I1 (79% identical), dog OR14I2 (78% identical), guinea pig OR14I1 (73% identical). Paralogues in human: OR14A16 (52% identical), OR14C36 (49% identical), OR14J1 (48% identical), OR14A2 (47% identical), OR14L1 (46% identical), OR14K1 (45% identical), OR5AP2 (43% identical), OR5I1 (42% identical), OR5AS1 (41% identical), OR5A1 (41% identical), OR5B12 (41% identical), OR5B21 (41% identical), and 84 more.
Diseases named in the same sentence as OR14I1 in open-access papers:
OR14I1 is named in the same sentence as 2 diseases in open-access papers, as found by Europe PMC text mining. Sharing a sentence is not in itself a finding about the gene and the disease. The quoted sentences say what the papers report.
HCMV infection (1 paper, 2019). "The role of the olfactory receptor OR14I1 in HCMV infection of epithelial cells was recently established in a genome-wide CRISPR/Cas9 screen on epithelial cells expressing Cas9 and a single-guide RNA library." (PMID 31336680, 2019). "In addition, they showed that OR14I1 downstream signaling mediated by the adenylate cyclase/protein kinase A/AKT pathway was required for HCMV infection." (PMID 31336680, 2019).
virus infection (1 paper, 2019). "The interaction of CD46 with one or several known entry factors (e.g., PDFGRα, Nrp2, CD147, and/or OR14I1) or yet to be identified factors may be required for virus infection by mediating viral endocytosis or viral fusion with the endosomal membrane." (PMID 31221976, 2019).